NFIB (nuclear factor I B)
Diseases named in the same sentence as NFIB in open-access papers (continued):
Sharing a sentence is not in itself a finding about the gene and the disease.
osteosarcoma (11 papers, 2016 to 2023). A usually aggressive malignant bone-forming mesenchymal neoplasm, predominantly affecting adolescents and young adults. "Lower NFIB is significantly associated with increased osteosarcoma cell migration, proliferation and colony formation." (PMID 36305631, 2022). "NFIB is also associated with osteosarcoma and sciatica in GWAS." (PMID 29765957, 2018). "In these experiments, FLAG-tagged NFIB was stably expressed in human osteosarcoma epithelial cell line U2OS, which is relatively easy to be synchronized." (PMID 37604829, 2023). "Lower NFIB levels were marginally associated with shorter OS and EFS in the TARGET‐osteosarcoma cohort." (PMID 36305631, 2022). "The lncRNA LINC00319 separately promotes the progression of cervical cancer via regulating the miR-147a/IGF1R axis and the osteosarcoma progression via sponging miR-455-3p to regulate NFIB." (PMID 35675043, 2022). "Conversely, NFIB has a tumour suppressor role in medulloblastoma, osteosarcoma and cutaneous squamous cell carcinoma." (PMID 27083054, 2016).
prostate carcinoma (11 papers, 2016 to 2026). A carcinoma that arises from epithelial cells of the prostate gland. "Interestingly, in 5/9 genes (55.5%), i.e., ABHD2, DICER1, GSK3B, NR3C1, and NFIB mutations were localized to functional domains of their corresponding proteins, which suggest them to be highly critical genes for prostate cancers." (PMID 36468011, 2022). "The high expression level of NFIB could indicate poor survival rate in more than 50% of prostate cancer patients (p < 0.05)." (PMID 36468011, 2022). "In the TCGA database, NFIA, NFIB and NFIC mRNA levels were significantly downregulated in prostate cancer patients." (PMID 32219034, 2020). "Moreover, ATAC-seq data suggest similar roles for NFIA and NFIB in the SHH subgroup of medulloblastoma, NFIB, and NFIX in prostate cancer, respectively." (PMID 39617063, 2025). "The other genes showing molecular alterations in prostate cancer samples from highest to lowest are as follows; FGF2 (94/4990; 1.9%), NFIB (86/4990; 1.7%), CEP43 (62/4990; 1.2%), GSK3B (99/8961; 1.1%), DICER1 (101/8961; 1.1%), NR3C1 (53/4990; 1.1%) and ABHD2 (28/4,990; 0.6%)." (PMID 36468011, 2022).
lung cancer (9 papers, 2015 to 2022). A malignant neoplasm involving the lung. "Transcriptome analysis has shown that NFIB is generally more highly expressed in human tumor tissues, which supports the important role of NFIB in tumor biological processes noted that NFIB is associated with key molecular events that drive nonsmall cell lung cancer metastasis." (PMID 33981484, 2021). "NFIB was unique to lung cancer participants compared to healthy smokers, targeted by five overexpressed miRNAs." (PMID 34071592, 2021). "The individual functions of NKX2-1, miR-200c, MYB, and NFIB in lung development and/or lung cancer have been widely documented." (PMID 25763778, 2015). "Interestingly, evidence shows that NFIB is a key epigenetic regulator during development and within lung cancer." (PMID 36569748, 2022). "Moreover, shH19 combined with Gefitinib treatment obviously increased the protein expression levels of PTEN and PDCD4, while decreased the expression levels of NFIB in lung cancer in vivo." (PMID 32281297, 2020). "Furthermore, the results demonstrated that shH19 administration significantly enhanced the expression levels of PTEN and PDCD4, while decreased the expression levels of NFIB in lung cancer." (PMID 32281297, 2020). "In lung cancer, expression of NFIA and NFIB was correlated with better prognosis." (PMID 32219034, 2020).
gastric cancer (8 papers, 2020 to 2022). A primary or metastatic malignant neoplasm involving the stomach. "For AKT/STAT3 signaling, it participated in NFIB-mediated EMT of gastric cancer." (PMID 33390776, 2021). "Furthermore, NFIB expression was upregulated in gastric cancer." (PMID 32219034, 2020). "Furthermore, NFIB expression was increased in gastric cancer." (PMID 32219034, 2020). "Moreover, NFIB could increase HER2 expression via upregulating circMAP7D1 in gastric cancer cells." (PMID 35655758, 2022). "For gastric cancer, NFIB and NFIX mRNA levels were not significantly different between tumor and normal tissues." (PMID 32219034, 2020).
triple-negative breast carcinoma (7 papers, 2014 to 2023). An invasive breast carcinoma which is negative for expression of estrogen receptor (ER), progesterone receptor (PR), and human epidermal growth factor receptor 2 (HER2). "On the one hand, NFIB promoted the proliferation and inhibited apoptosis of triple-negative breast cancer (Liu R.-Z." (PMID 35655758, 2022). "In Small cell lung cancer (SCLC) and triple negative breast cancer, NFIB was highly expressed than normal tissues and repressed apoptosis to promote cell proliferation." (PMID 24949940, 2014).
glioblastoma (6 papers, 2016 to 2025). The most malignant astrocytic tumor (WHO grade IV). "In contrast, in oral cancer and glioblastoma, NFIB acts as a tumor suppressor." (PMID 40943553, 2025). "To examine this further and compare NFIB and NFIB4, we performed proximity labeling experiments in three cell lines: HEK293, SH-SY5Y neuroblastoma cells, and U251 MG glioblastoma cells." (PMID 39617063, 2025). "For example, while both NFIA and NFIB are required for in vitro and in vivo glioblastoma growth, NFIA overexpression leads to cell proliferation and migration, whereas NFIB suppresses tumor growth and promotes glial differentiation." (PMID 39617063, 2025).
leukemia (6 papers, 2011 to 2021). A malignant (clonal) hematologic disorder, involving hematopoietic stem cells and characterized by the presence of primitive or atypical myeloid or lymphoid cells in the bone marrow and the blood. "Two of the 59 inverse miRNA:mRNA target pairs we identified have been validated: miR-21:NFIB (an oncogenic interaction) in leukemia cells and miR-195:CCND1 (a tumor-suppressive interaction) in hepatocellular carcinoma." (PMID 21375733, 2011). "In addition, there were no studies of CANT1, KIAA1549, and NFIB on leukemia in previous literatures; therefore, the association between these genes and leukemia should be further investigated." (PMID 32638549, 2020). "Analysis of NFIB expression by RNA-seq data of 100 leukemia-lymphoma cell lines (E-MTAB-7721) and RQ-PCR of eight HL cell lines revealed enhanced NFIB transcription in SUP-HD1 cells." (PMID 33539429, 2021). "Thus NFIB interacts with miR-21 and form a double-negative feedback loop for the survival of leukemia HL-60." (PMID 24949940, 2014).
astrocytoma (5 papers, 2016 to 2024). "In pathology, NFIA and NFIB are known to induce cellular differentiation in high-grade astrocytoma." (PMID 39404397, 2024). "Here we report that NFIB expression correlates inversely with astrocytoma grade." (PMID 27083054, 2016). "In all three datasets NFIB expression inversely correlated with astrocytoma grade." (PMID 27083054, 2016). "NFIB expression correlates inversely with astrocytoma grade and is lowest in mesenchymal GBM." (PMID 27083054, 2016). "We first investigated whether the level of NFIB expression corresponds to the degree of differentiation, or grade, of astrocytoma." (PMID 27083054, 2016).
Intellectual disability (5 papers, 2021 to 2025). "The duplication in the 9p region involves the NFIB gene, the abnormality of which has been confirmed to be associated with acquired megalencephaly with intellectual disability, mainly characterized by intellectual disability, hypotonia, and seizures." (PMID 40406061, 2025). "NFIB (nuclear factor I/B) too is associated with intellectual disability and acts as a transcription activator of GFAP, which is found to be significantly upregulated in all AD stages in this work and is also essential for proper brain development." (PMID 39299805, 2024). "Mutations in NFIB are known to be pathogenic for intellectual disability and macrocephaly, as well as pulmonary dysplasia in humans and mice." (PMID 35433561, 2022). "Recent studies have shown that mutations in NFIB are associated with intellectual disability and macrocephaly." (PMID 35433561, 2022). "Mutations in NFIB cause intellectual disability and macrocephaly." (PMID 35433561, 2022). "Clinical correlation analysis indicates that the duplication of the NFIB gene in this case may synergistically exacerbate neurodevelopmental abnormalities such as intellectual disability and hypotonia." (PMID 40406061, 2025). "In particular, NFIB K126E mutation (at the site corresponding to K125 residue in NFIA) causes a severe loss of transcriptional activity and is one of the variants associated with intellectual disability and macrocephaly." (PMID 33973697, 2021).
keratoconus (5 papers, 2014 to 2022). A degenerative, structural disorder of the eye, characterized by a cone-shaped protrusion of the cornea. "Similarly, other candidate genes identified by GWAS including HGF, RAB3GAP1, LOX, MPDZ, NFIB, BANP, and ZNF469 may be important risk factors for keratoconus and require replication studies in other populations." (PMID 25254113, 2014). "Overall, we found a significant negative correlation of effect sizes across CCT and keratoconus (r = −0.62, P = 5.30 × 10−5), this correlation was largely unchanged if the known SNPs in ZNF469, FOXO1, COL5A1 and MPDZ/NFIB were removed from the analysis (r = −0.61, P = 2.04 × 10−4)." (PMID 29760442, 2018).
lipoma (5 papers, 2012 to 2024). A benign, usually painless, well-circumscribed lipomatous tumor composed of adipose tissue. "HMG2A-NFIB fusions have been reported in lipomas while other tumour-associated translocations involving NFIB include MPDZ-NFIB, NFIB-FREM, NFIB-HEATR5B, NFIB-STRN and NFIB-ZDHHC21." (PMID 27083054, 2016). "However, it is important to note that exactly the same fragment of NFIB is fused with HMGA2 and HMGIC genes in lipoma and pleomorphic adenoma, respectively." (PMID 27533466, 2016).
medulloblastoma (5 papers, 2014 to 2025). A malignant, invasive embryonal neoplasm arising from the cerebellum. "With this in mind, we assessed key transiently activated neural transcription factors (MATH1, NHLH1), and other temporally activated genes (NEUROD1, NHLH2, NFIB, LPPR4, DPYSL3, NEUROD2) expressed throughout granule neuron differentiation, in the medulloblastoma subgroups." (PMID 25412507, 2014).
colon carcinoma (4 papers, 2018 to 2025). "Overexpression of NFIB in colon carcinoma Caco-2/TC7 cells caused significant NFIB-dependent inhibition of ABCB1 and ABCG2 gene expression." (PMID 40554316, 2025). "To do this, we assessed the extent of NFIB regulation using colon carcinoma Caco-2/TC7 cells, a model previously employed to study CLZ’s intestinal transporters." (PMID 40554316, 2025). "MiR-302a was generally downregulated in colon cancer; its overexpression directly inhibits metastasis and CET resistance by silencing nuclear factor I B (NFIB) and CD44 targets." (PMID 34503164, 2021).
cutaneous squamous cell carcinoma (4 papers, 2014 to 2022). "In this study, we identified Nuclear Factor I/B (NFIB) as one of the targets of miR-365 which was previously verified as an onco-miR in cutaneous squamous cell carcinoma (CSCC)." (PMID 24949940, 2014).
esophageal cancer (4 papers, 2021 to 2025). A primary or metastatic malignant neoplasm involving the esophagus. "The expression of miR-149-5p was low, while LincDRAIC and NFIB were highly expressed in esophageal cancer cells." (PMID 34722295, 2021). "Down-regulation of DRAIC, NFIB and up-regulation of miR-149-5p can inhibit the proliferation, invasion, and promote apoptosis and autophagy of esophageal cancer cells at the meanwhile." (PMID 34722295, 2021). "And in breast cancer cell lines, lncRNA DRAIC was up-regulated by FOXP3 and promoted cell migration and invasion via the miR-432-5p/SLBP axis.Moreover, lncRNA DRAIC improved esophageal cancer Eca-109 and EC9706 cell invasion through binding to miR-149-5p, which regulated NFIB levels." (PMID 35992823, 2022). "Similarly, lncRNA DRAIC was found to inhibit cell autophagy in esophageal cancer Eca-109 and EC9706 cells acting as ceRNAs to modulate the expression of NFIB by quenching miR-149-5p." (PMID 35992823, 2022). "Similarly, lncRNA DRAIC led to cell proliferation in esophageal cancer Eca-109 and EC9706 cells through the miR-149-5p/NFIB axis." (PMID 35992823, 2022).
hepatocellular carcinoma (3 papers, 2011 to 2023). A malignant tumor that arises from hepatocytes. "During the transformation of hepatocytes into hepatoma cell, the regulatory effect of NFIB on ASS1 and CPS1 changed." (PMID 35655758, 2022). "We found that knockdown of NFIB can only augment the expression of CPS1 and ASS1 in normal hepatocyte but not in hepatoma cell, implying its stage-specific effect." (PMID 35655758, 2022).
liver cancer (3 papers, 2020 to 2024). An epithelial or non-epithelial malignant neoplasm that arises from the liver. "We then wondered whether knockdown of NFIB would cause the same results in human liver cancer or normal liver cell lines." (PMID 35655758, 2022). "Besides, decreased NFIC expression level was associated with poor PFS and NFIB expression was uncorrelated with OS in liver cancer patients." (PMID 32219034, 2020). "It is expected to provide a new strategy for the treatment of liver cancer by analyzing the effect of NFIB on the metabolic changes and tumorigenesis mechanism of liver cancer." (PMID 35655758, 2022). "Here we provide evidence showing that NFIB, a nuclear gene expression regulator, links urea cycle to the liver cancer." (PMID 35655758, 2022). "Moreover, it has been verified that LOXL1-AS1 sponges miR-377–3p, the other direct target of LoxL1-AS1, and miR-377–3p acts as an upstream direct regulator of nuclear factor I B (NFIB) gene in liver cancer." (PMID 39136001, 2024). "NFIB may be able to protect liver cancer cells from oxidative stress and promote their survival in the presence of chemotherapy." (PMID 39136001, 2024). "Moreover, urea cycle enzymes (ASS1 and CPS1) are inhibited in liver cancer, so the expression of them have decreased in liver cancer cells, and the increase of ASS1 and CPS1 caused by knocking down NFIB becomes insignificant." (PMID 35655758, 2022). "In our study, we constructed hepatocyte-specific NFIB gene knockout mice with CRISPR/Cas9 technology (Nfib−/−; Alb-cre), and induced liver cancer mouse model by intraperitoneal injection of DEN/CCl4." (PMID 35655758, 2022). "Specific knockout of liver NFIB leads to increased expression of ASS1 and CPS1, which promotes the occurrence of liver cancer by affecting the urea cycle." (PMID 35655758, 2022). "Therefore, It is proposed that LoxL1-AS1/miR-377–3p/NFIB axis promotes proliferation, migration and EMT of liver cancer." (PMID 39136001, 2024). "Nuclear Factor I B (NFIB) has been reported to promote tumor growth, metastasis, and liver regeneration, but its mechanism in liver cancer is not fully elucidated." (PMID 35655758, 2022).
lymphoma (3 papers, 2016 to 2023). A malignant (clonal) proliferation of B- lymphocytes or T- lymphocytes which involves the lymph nodes, bone marrow and/or extranodal sites. "Importantly, NFIB is identified as a hub gene that is overexpressed across many lymphoma RNA-sequencing datasets." (PMID 36672402, 2023).
metastatic tumors (3 papers, 2017 to 2020). "Copy number amplification at the NFIB locus and protein overexpression in the metastatic tumors in the GEMM and human cell lines derived from metastasis prompted multiple investigations into a role for NFIB in SCLC21,27,28,103,104." (PMID 31827074, 2019). "Linear regression analysis comparing the expression profiles of our various genes of interest reveals that there is a significant positive correlation between BRN2 and NFIB expression in human metastatic tumours (P < 0.0046)." (PMID 28119061, 2017).
neuroblastoma (3 papers, 2016 to 2025). Neuroblastoma (NB) is the most common solid, extracranial childhood tumor. "We found that the CDON regulatory region was occupied by NFIA and NFIB, aligning with findings that NFIB represses CDON in neuroblastoma cells." (PMID 39617063, 2025).
Sciatica (3 papers, 2016 to 2025). Pain in the lower back and hip radiating in the distribution of the sciatic nerve. "The strongest association signal (p = 1.30x10-8) for sciatica in our present study was obtained for a single base insertion -/G (chr9:14344410:I; rs71321981) within NFIB gene at locus 9p22.3." (PMID 27764105, 2016). "In summary, our results suggest a novel locus, 9p22.3 (NFIB), which may be involved in susceptibility to sciatica." (PMID 27764105, 2016).
acinic cell carcinoma (2 papers, 2023). "Several genes that are known to be important in ACC tumors are highlighted with black dots at right, including (from top to bottom) EN1, GABRP, MYB, MYBL1 and NFIB, all of which are expressed more highly in the ACC tumors than in the normal salivary gland or acinic cell carcinoma samples (at left)." (PMID 36900183, 2023).
cervical cancer (2 papers, 2020 to 2022). A primary or metastatic malignant neoplasm involving the cervix. "The Oncomine database showed significant differences in mRNA expression of NFIB and NFIC between cervical cancer and normal tissues." (PMID 32219034, 2020).
clear cell carcinoma (2 papers, 2017 to 2020). "For example, the expression of NFIA and NFIB was reduced in kidney chromophobe cell carcinoma but not in papillary or clear cell carcinoma; however, mRNA expression levels were elevated." (PMID 32219034, 2020).
depression (2 papers, 2020 to 2022). "Recently, a study on lymphoblastoid cell lines from depression patients treated with citalopram reported a significant association of NFIB expression with improvement in depression scale." (PMID 36362329, 2022). "Results from the STAR*D study showed a marginal association of treatment-resistant depression with NFIB (p = 0.068) but not with GAD1 (p = 0.23) and TBC1D9 (p = 0.27)." (PMID 32612257, 2020). "In our biomarker analysis, expression of GAD1, NFIB, and TBC1D9 showed associations with response status, remission status, and improvement in depression scale, respectively, but not with treatment resistance." (PMID 32612257, 2020).
esophagogastric junction adenocarcinoma (2 papers, 2018 to 2020). "The roles of NFIA and NFIB in esophageal squamous cell carcinoma (ESCC) and esophagogastric junction adenocarcinoma (EJA) remain poorly known." (PMID 29577671, 2018). "In a previous study, high NFIA expression was shown an independent predictor of poor prognosis in esophageal squamous carcinoma, and high NFIB expression was a negative prognostic value in esophagogastric junction adenocarcinoma." (PMID 32219034, 2020).
lung adenocarcinoma (2 papers, 2020 to 2021). A carcinoma that arises from the lung and is characterized by the presence of malignant glandular epithelial cells. "Lung adenocarcinoma patients with NFIB gene alteration showed better DFS compared with lung adenocarcinoma patients without NFIB gene alteration." (PMID 32219034, 2020). "Decreased NFIA and NFIB expression predicted worse OS and FP in lung adenocarcinoma patients." (PMID 32219034, 2020). "Low mRNA expression of NFIA and NFIB was significantly associated with OS and first progression in lung adenocarcinoma, but not in lung squamous cell carcinoma." (PMID 32219034, 2020).